SIVA1 (SIVA1 apoptosis inducing factor)
Description:
Induces CD27-mediated apoptosis. Inhibits BCL2L1 isoform Bcl-x(L) anti-apoptotic activity. Inhibits activation of NF-kappa-B and promotes T-cell receptor-mediated apoptosis.
Synonyms: CD27BP; SIVA; Siva-1; Siva-2
Tractability: PROTAC: ubiquitination databases record sites on it.
Gene: Protein-coding gene on chromosome 14 (104,753,131 to 104,768,494, forward strand). Ensembl gene ENSG00000184990.
Subcellular location: Cytoplasm; Nucleus
Subcellular location (Human Protein Atlas): Nucleoplasm
Gene Ontology:
Molecular function: CD27 receptor binding; protein binding; virus receptor activity; tumor necrosis factor receptor binding
Biological process: extrinsic apoptotic signaling pathway; symbiont entry into host cell
Cellular component: nucleoplasm; cytoplasm; nucleus
Genetic constraint (gnomAD): Loss-of-function variants: 11 observed, 18.73 expected, observed/expected ratio (o/e) 0.59, 90% interval 0.37 to 0.97. The upper end of that interval is the gene's LOEUF score, 0.97, which puts it in group 4 of 6, group 1 being the genes least tolerant of losing a copy. Missense variants: 239 observed, 238.38 expected, observed/expected ratio (o/e) 1, 90% interval 0.9 to 1.12. Synonymous variants: 130 observed, 107.54 expected, observed/expected ratio (o/e) 1.21, 90% interval 1.05 to 1.4.
Homologues: Orthologues: chimpanzee SIVA1 (100% identical), macaque SIVA1 (95% identical), dog SIVA1 (78% identical), pig SIVA1 (77% identical), rat Siva1 (75% identical), guinea pig SIVA1 (71% identical), mouse Siva1 (71% identical), tropical clawed frog siva1 (40% identical), zebrafish siva1 (39% identical).
Diseases named in the same sentence as SIVA1 in open-access papers:
SIVA1 is named in the same sentence as 14 diseases in open-access papers, as found by Europe PMC text mining. Sharing a sentence is not in itself a finding about the gene and the disease. The quoted sentences say what the papers report.
breast carcinoma (3 papers, 2016 to 2024). "For example, expression of Siva1, which acts as negative regulator of EMT, and post-translational modification of stathmin, a microtubule destabilizer, are different in primary tumors and metastatic tumors in breast cancer patients." (PMID 26877098, 2016).
colon cancer (2 papers, 2020 to 2021).
colorectal cancer (2 papers, 2009 to 2025). A primary or metastatic malignant neoplasm that affects the colon or rectum. "Similarly, FTO overexpression enhanced chemoresistance in colorectal cancer by modulating SIVA1-mediated apoptosis." (PMID 39990672, 2025).
gastric cancer (2 papers, 2022 to 2024). A primary or metastatic malignant neoplasm involving the stomach. "To investigate the mechanism by which Siva-1 reverses MDR in human gastric cancer cells, we knocked down Siva-1 in MKN-28/VCR cells." (PMID 37303491, 2022). "Siva-1 plays an important role in regulating the sensitivity of gastric cancer cells to certain chemotherapies." (PMID 37303491, 2022). "Studies have analyzed MDR1 and MRP1 gene regulation by over-expressing Siva-1 and subsequently upregulating NF-κB in gastric cancer cell lines." (PMID 37303491, 2022). "In our previous study, we showed that overexpressed Siva-1 decreased the apoptosis of gastric cancer cells." (PMID 37303491, 2022). "To confirm the correlation between Siva-1 and MDR in gastric cancer cells, we inhibited the expression of Siva-1 and studied the phenomenon of MDR reversal." (PMID 37303491, 2022). "The present study aimed to determine the specific role of Siva-1 in anticancer drug resistance in gastric cancer in vivo and in vitro and preliminarily reveal the mechanism." (PMID 37303491, 2022). "In the current study, we hypothesized that suppressed NF-κB levels mediated by Siva-1 could decrease gastric cancer cell metastasis and reverse MDR." (PMID 37303491, 2022). "The results indicated that inhibition of Siva-1 expression prevented drug efflux in gastric cancer cells, increased the sensitivity of cells to the chemotherapeutic drug VCR, decreased the number and size of cancer cell colonies, and increased the cell apoptosis rate." (PMID 37303491, 2022). "Thus, these were chosen for subsequent experiments to further explore the function of Siva-1 in reversing MDR in gastric cancer." (PMID 37303491, 2022). "Our previous study indicated that Siva-1 overexpression inhibited apoptosis and enhanced MDR in a VCR-resistant gastric cancer cell line, and we also revealed that Siva-1 increased the colony formation and invasion of cells." (PMID 37303491, 2022). "he current study demonstrated that the downregulation of Siva-1, which functions as a regulator of MDR1 and MRP1 gene expression in gastric cancer cells by inhibiting PCBP1/Akt/NF-κB signaling pathway expression, enhanced the sensitivity of gastric cancer cells to certain chemotherapies." (PMID 37303491, 2022). "Given the crucial role of Siva-1 in the regulation of MDR and gastric cancer cell metastasis, Siva-1 could serve as a novel potential anticancer agent designed to overcome chemotherapeutic resistance mechanisms." (PMID 37303491, 2022).
non-small cell lung carcinoma (2 papers, 2021 to 2024). A group of at least three distinct histological types of lung cancer, including non-small cell squamous cell carcinoma, adenocarcinoma, and large cell carcinoma. "Van Nostrand and others showed in non-small cell lung cancer that SIVA-1 knockdown reduces energy production and results in autophagy, suggesting that SIVA-1 is necessary to facilitate tumorogenesis." (PMID 35083225, 2021).
tumor (10 papers, 2015 to 2024). "The tumor weights in the Siva-1 knockdown group (7.13 ± 1.47 g) were significantly lower than those in the MKN-28/VCR-shRNA-NC group (10.31 ± 2.01 g) and MKN-28/VCR group (11.14 ± 1.72 g) (p < 0.05), indicating better health." (PMID 37303491, 2022). "Furthermore, SIVA-1 overexpression with DDP treatment synergistically inhibited tumor growth in vivo by increasing PCBP1 and decreasing Bcl-2 and Bcl-xL expression." (PMID 38947376, 2024). "We investigated E3 ubiquitin ligases SIVA1 and ULF that regulate p14ARF (p19ARF in mice) tumor suppressor." (PMID 35767594, 2022). "Additionally, in gastric cancer FTX exerts a similar functional role via the miR-144/ZFX and miR-215-3p/SIVA1 regulatory axis in promoting tumorigenesis; in addition, FTX was upregulated in tumor tissues in comparison to adjacent non-tumor tissues and correlated to poor prognosis." (PMID 35054794, 2022). "There were also genes that are of insignificant expression in tumor cells that increase in expression in KO cells, e.g. THBS3, IL2RG, SPRR3, TGM2, HMOX1 and TMEM62 or are lower in expression in tumor cells and significantly decreased in KO cells such as MAN1A1, CES1, STCBP6, SIVA1 and TMEM40." (PMID 31797958, 2019). "In addition, recently published data indicate that SIVA1 is not a strictly pro-apoptotic factor, but also a potent suppressor of tumor metastasis." (PMID 26255627, 2015).
cancer (8 papers, 2009 to 2024). A tumor composed of atypical neoplastic, often pleomorphic cells that invade other tissues. "Low Siva1 expression is associated with poorer OS and lower tumor differentiation in cancer patients." (PMID 37256211, 2023). "Differential edge between Bcl-xL and SIVA1-NM_006427 hints at role of Bcl-xL association with SIVA1 in cancer." (PMID 25034693, 2014). "In cancer studies SIVA-1 has been found to have a role as pro- or anti-malignant factor, depending on cellular context." (PMID 35083225, 2021). "Studies carried out in ovarian and cervical cancer cells show that SIVA-1 suppresses migration and invasion of cancer cells, and overall prevents metastasis through phosphorylation of stathmin, a microtubule destabilizer." (PMID 35083225, 2021). "Many studies have demonstrated an anti-apoptotic role of Siva-1 in several malignant tumors." (PMID 37303491, 2022). "The differential edge (red) between Bcl-xL and SIVA1-NM_006427 hints at role of Bcl-xL in cancer." (PMID 25034693, 2014).
infection (2 papers, 2021 to 2022). The state of being infected such as from the introduction of a foreign agent such as serum, vaccine, antigenic substance or organism. "We were also able to recapitulate effects of H. pylori on ULF and SIVA1 in the murine gastroids derived from the antropyloric region after their infection with H. pylori strains 7.13 or PMSS1 in vitro (respectively)." (PMID 35767594, 2022). "Siva1–205 and Nfkb1–210 lncRNAs were of higher abundance during RH infection of wild type and Myd88 KO macrophages." (PMID 33622246, 2021). "We also concluded that whereas SIVA1 regulates ARF in uninfected cells and at initial stages of infection (plausibly until SIVA1 levels are sufficiently decreased), induction of ULF is primarily responsible for downregulation of ARF in H. pylori-infected cells." (PMID 35767594, 2022). "Expression of SIVA1 and ULF proteins were assessed in the murine stomach after infection with H. pylori strain PMSS1 for 10 days using IHC and Western blotting." (PMID 35767594, 2022). "We found that whereas infection with wild type strain PMSS1 leads to significant increase of ULF levels and downregulation of SIVA1, as well as p19ARF in the corpus and antrum, cagE- mutant has a diminished ability to do so, suggesting an important role of the T4SS signaling." (PMID 35767594, 2022).
SIVA1 also shares sentences with these, for which no sentence is quoted: breast tumor (2 papers); cervical cancer (1); liver cancer (1); metastatic tumors (1); ovarian carcinoma (1); Salmonella Infections (1).